TP53INP2 (tumor protein p53 inducible nuclear protein 2)
Diseases named in the same sentence as TP53INP2 in open-access papers (continued):
Sharing a sentence is not in itself a finding about the gene and the disease.
retinoblastoma (1 paper, 2024). A malignant tumor that originates in the nuclear layer of the retina.
thyroid cancer (1 paper, 2025). "Furthermore, TP53INP2 has been identified as a potential biomarker for thyroid cancer." (PMID 40755754, 2025).
cancer (17 papers, 2010 to 2025). A tumor composed of atypical neoplastic, often pleomorphic cells that invade other tissues. "Concordantly, ERK5 inhibition or genetic deletion, by stabilizing TP53INP2, sensitizes cancer cells to the apoptosis induced by recombinant TRAIL and TRAIL/FasL expressed by Natural Killer cells." (PMID 37919293, 2023). "Mechanistically, ERK5 phosphorylates and induces ubiquitylation and proteasomal degradation of TP53INP2, resulting in cancer cell resistance to TRAIL." (PMID 37919293, 2023). "We found that ERK5 kinase activity confers resistance to the cytotoxicity exerted by DR agonists in cancer cells, by phosphorylating and inducing proteasomal degradation of TP53INP2." (PMID 37919293, 2023). "Meanwhile, based on the GSEA analysis (GSE40435 and GSE14762), TP53INP2 expression of the cancer tissues was lower than the normal tissues." (PMID 35615533, 2022). "Screening to cancer cell lines also implied that those cells with higher protein expressions of TP53INP2 are more prone to being the ones of receptor-induced apoptosis." (PMID 35615533, 2022). "TP53INP2 has been shown to participate in many cancers and is involved in multiple stages of autophagy." (PMID 35521536, 2022). "TP53INP2 is a key regulator of skeletal muscle and regulates muscle atrophy due to cancer cachexia by activating autophagy." (PMID 36419834, 2022). "It has recently been demonstrated that alternative splicing of exon 2 near the 5′ un-translated region of TP53INP2 is a key event downstream of hnRNPA2 that is necessary for cancer cells to migrate and invade through the extracellular matrix." (PMID 23717325, 2013). "It is crucial to further understand how to control hnRNPA2-mediated TP53INP2 splicing to avoid cancer cell migration, and to retain TP53INP2-mediated autophagy, which synergizes with TP53INP1-induced autophagy." (PMID 23717325, 2013). "These miRNAs target the tumour suppressor genes, PTEN, TP53INP1 and TP53INP2, and other proteins involved in cancer development and progression, such as BCL2L2, ERBB4, MAPK9, MCL1, MYCN, VEGFA and VEGFR1." (PMID 20668671, 2010). "Together, our preliminary results suggest that ERK5 inhibition could enhance the NK-TRAIL/FasL-induced apoptosis in cancer cells, most likely by regulating TP53INP2 protein stability." (PMID 37919293, 2023). "Thus, ectopic overexpression of TP53INP2 sensitized cancer cells to DR ligands-induced apoptosis, suggesting modulation of TP53INP2 proteostasis as a new strategy to improve the apoptosis induced by DR ligands." (PMID 37919293, 2023). "ZSCAN18 inhibits malignant behavior in GC by binding to the TP53INP2 promoter region and promoting autophagy, which may contribute to the development of a promising target for carcinoma diagnosis and treatment." (PMID 36650573, 2023). "Dysregulation of Tp53INP2 expression was found differently in several types of cancer tissues." (PMID 29104726, 2017). "If so, TP53INP2 proteostasis could emerge as a central node regulating sensitivity/resistance to DR agonist cytotoxicity, by integrating oncogenic signaling pathways involved in cancer cell survival." (PMID 37919293, 2023). "Thus, loss of TP53INP2 does not affect autophagy flux detectably in this cancer cell line." (PMID 41368677, 2025). "A set of genes, including PNRC1, HERPUD1, TP53INP2, Tob1, and SAT1, were downregulated in patients with different cancer types, and their decreased expression was correlated with poorer prognosis and shorter survival time." (PMID 39861074, 2024). "While TP53INP2 induces autophagy via mechanisms similar to TP53INP1, an alternative splicing product of TP53INP2 RNA due to hnRNPA2 induces cancer cell migration." (PMID 23717325, 2013).
cancer (continued). "First, the relationship between TP53INP2 and the sensitivity of AML cells to TRAIL was determined by bioinformatics analysis of Cancer Cell Line Encyclopedia datasets, Cell Counting Kit-8 assays, flow cytometry (FCM) and cell line-derived xenograft (CDX) mouse models." (PMID 38909249, 2024). "Despite the important roles of TP53INP2 in cancer cell autophagy and migration, it is not clear how TP53INP2 expression is controlled in cancer cells." (PMID 23717325, 2013). "As such, restoration of TP63INP1 and TP53INP2 expression without the induction of hnRNPA2-mediated TP53INP1 RNA alternative splicing would ideally induce cancer cell cycle arrest, apoptosis, and autophagy, therefore simultaneously inducing binary cell death for a more effective therapy." (PMID 23717325, 2013).
tumor (17 papers, 2013 to 2026). "Combined with immune infiltration analysis showing a positive correlation between TP53INP2 expression and M0 macrophage infiltration, these findings suggested that this gene may influence the tumor immune microenvironment by regulating tumor-associated macrophages (TAMs)." (PMID 40755754, 2025). "TP53INP2 not only plays a key role in cellular metabolism but also regulates tumor cell invasiveness and migration." (PMID 40755754, 2025). "The expression analysis of key genes (PNRC1, HERPUD1, TP53INP2, Tob1, and SAT1), which is typically silenced in various tumour tissues and associated with poor prognosis and short survival time, revealed their upregulation upon 24 h treatment with L1." (PMID 39861074, 2024). "ZSCAN18 acted as a transcription factor and played an important role in binding to the promoter of tumor protein 53-induced nuclear protein 2 (TP53INP2), and we also confirmed the anti-tumor effect of TP53INP2 in GC." (PMID 36650573, 2023). "Overexpressed TP53INP2 is found to suppress the activity, migration, and invasion of ccRCC cells, thereby inhibiting tumor growth in mice and promoting cell apoptosis." (PMID 35615533, 2022). "Our further experiments would be conducted in animals for the detection on TP53INP2's effects on the tumor evolution." (PMID 35615533, 2022). "Current research shows that TP53INP2 either can promote the development or inhibit the proliferation of tumor cells depending on the tumor types." (PMID 35846146, 2022). "All the results demonstrated that the inhibitory effects of autophagy-related gene TP53INP2 work out in tumor growth in both vitro and vivo." (PMID 35615533, 2022). "Overexpression of TP53INP2 inhibited ccRCC cellular proliferation, migration, and invasion, as well as the tumor growth of mice." (PMID 35615533, 2022). "TP53INP2 has not only the function on tumor inhibition but also on the ability to inhibit tumor metastasis, which was consistent with our results." (PMID 35615533, 2022). "Among these genes, we identified the tumor-related gene TP53INP2, which is a downstream gene regulated by MUC16." (PMID 34150633, 2021). "As a tumor suppressor, TP53INP2 may participate in a previously unrecognized Ast-related neural apoptosis pathway, potentially contributing to neurodegeneration." (PMID 40894028, 2025). "Meanwhile, as a tumor suppressor, TP53INP2 also promote cellular apoptosis under pathological conditions, which may further exacerbate Exc degeneration." (PMID 40894028, 2025). "Our results also showed that TP53INP2 has tumor inhibition function." (PMID 35615533, 2022). "Collectively, we demonstrated that the tumor suppressor role of glycosylated CGA-T1 in PDAC is associated with its negative regulation of autophagy through multiple pathways, including PI3K/Akt/mTOR and TP53INP2 pathways." (PMID 35521536, 2022). "We found that the TP53INP2's expression in ccRCC turned out a conspicuous lower level versus normal tissues, and it was proportional to the survival rate of patients with ccRCC, suggesting that TP53INP2 may be a tumor suppressor gene." (PMID 35615533, 2022). "After overexpressing TP53INP2 in vivo, the size of the tumor was significantly reduced." (PMID 35615533, 2022). "TUNEL assay revealed that the overexpression of TP53INP2 promoted apoptosis of tumor cells." (PMID 35615533, 2022). "Furthermore, some oncogenic genes like EGFR, CDK6, YAP1, and MMP7 were amplified in the TP53INP2-low patients while some tumor suppressor genes including CDKN2A, KLF6, and PTEN were deleted." (PMID 33897760, 2021). "However, like TP53INP1, TP53INP2 is involved in the control of tumor development by modulating autophagy." (PMID 23717325, 2013). "Thus we hypothesized that TP53INP2 protein might also act as a tumor suppressor." (PMID 25650662, 2015).
tumor (continued). "Overexpression of TP53INP2 on cellular proliferation, migration, and apoptosis of ccRCC was verified in the ways of performing CCK-8, wound scrape, transwell and flow cytometry assays in vitro, and a mice tumor model in vivo." (PMID 35615533, 2022). "To validate the expression levels of the eight key genes (LIMS2, TP53INP2, IRAK3, STX2, CYP27A1, IL11RA, KCNMB1, and PDLIM7) in tumor and non-tumor samples, we analyzed their expression in TCGA and GSE7476 datasets." (PMID 40755754, 2025).
infection (2 papers, 2016 to 2025). The state of being infected such as from the introduction of a foreign agent such as serum, vaccine, antigenic substance or organism. "RCAN1, SLC6A6, RHOB, DUSP, TGM3, and TP53INP2 DEGs, which are related to DNA damage-induced apoptosis, autophagy, the cell cycle, and inflammatory repression, were also upregulated after vPdR-36U infection." (PMID 40006915, 2025).
neurodegenerative disease (1 paper, 2022). A disorder of the central nervous system characterized by gradual and progressive loss of neural tissue and neurologic function. "TP53INP2 is highly expressed in sympathetic neuron axons and regulates axon growth by enhancing NGF-TrkA signaling, a pathway implicated mainly in neurodegenerative diseases." (PMID 35682902, 2022).
TP53INP2 also shares sentences with these, for which no sentence is quoted: cervical cancer (1 paper); Clear Cell Renal Cell Cancer (1); esophageal cancer (1); Huntington disease (1); Hyperglycemia (1); lymphoma (1); movement disorder (1); neurodevelopmental disorder (1); Parkinson disease (1); schizophrenia (1); type 2 diabetes (1); vitiligo (1).